SAR1A (secretion associated Ras related GTPase 1A)
Description:
Small GTPase that cycles between an active GTP-bound and an inactive GDP-bound state and mainly functions in vesicle-mediated endoplasmic reticulum (ER) to Golgi transport. The active GTP-bound form inserts into the endoplasmic reticulum membrane where it recruits the remainder of the coat protein complex II/COPII. The coat protein complex II assembling and polymerizing on endoplasmic reticulum membrane is responsible for both the sorting of cargos and the deformation and budding of membranes into vesicles destined to the Golgi. The GTPase activity of SAR1 by controlling the timing of COPII budding regulates the size of the formed vesicles and is important for cargo selection depending on their size. Together with SEC16A, forms the organized scaffold defining endoplasmic reticulum exit sites (ERES), some specific domains of the endoplasmic reticulum where COPII vesicles form. In addition to its role in vesicle trafficking, can also function as a leucine sensor regulating TORC1 signaling and more indirectly cellular metabolism, growth and survival. In absence of leucine, interacts with the GATOR2 complex via MIOS and inhibits TORC1 signaling. The binding of leucine abrogates the interaction with GATOR2 and the inhibition of the TORC1 signaling. This function is completely independent of the GTPase activity of SAR1B.
Synonyms: SAR1; SARA; SARA1; masra2
Tractability: Small molecule: a structure with a bound ligand is known. Antibody: UniProt places it where antibodies can reach, with high confidence. PROTAC: ubiquitination databases record sites on it; its protein half-life has been measured.
Gene: Protein-coding gene on chromosome 10 (70,147,289 to 70,170,905, reverse strand). Ensembl gene ENSG00000079332.
Subcellular location: Endoplasmic reticulum membrane; Golgi apparatus, Golgi stack membrane; Cytoplasm, cytosol; Lysosome membrane
Subcellular location (Human Protein Atlas): Endoplasmic reticulum
Gene Ontology:
Molecular function: amino acid sensor activity; G protein activity; GTPase activity; protein binding; GTP binding
Biological process: cellular response to leucine starvation; COPII vesicle coating; COPII-coated vesicle cargo loading; endoplasmic reticulum to Golgi vesicle-mediated transport; lipoprotein transport; negative regulation of TORC1 signaling; regulation of TORC1 signaling; membrane organization; positive regulation of ER to Golgi vesicle-mediated transport; vesicle organization; intracellular protein transport
Cellular component: COPII vesicle coat; endoplasmic reticulum; endoplasmic reticulum exit site; endoplasmic reticulum membrane; lysosomal membrane; cytosol; Golgi cisterna membrane
Genetic constraint (gnomAD): Loss-of-function variants: 0 observed, 12.29 expected, observed/expected ratio (o/e) 0, 90% interval 0 to 0.24. The upper end of that interval is the gene's LOEUF score, 0.24, which puts it in group 1 of 6, group 1 being the genes least tolerant of losing a copy. Missense variants: 84 observed, 166.42 expected, observed/expected ratio (o/e) 0.5, 90% interval 0.42 to 0.61. Synonymous variants: 44 observed, 56.16 expected, observed/expected ratio (o/e) 0.78, 90% interval 0.61 to 1.01.
Homologues: Orthologues: chimpanzee SAR1A (100% identical), mouse Sar1a (99% identical), rabbit SAR1A (99% identical), rat Ppa1 (99% identical), dog SAR1A (99% identical), guinea pig SAR1A (99% identical), pig SAR1A (99% identical), tropical clawed frog sar1a (96% identical). Paralogues in human: SAR1B (90% identical), TRIM23 (31% identical), ARF6 (31% identical), ARL14 (31% identical), ARF1 (30% identical), ARF4 (30% identical), ARF5 (30% identical), ARL4D (30% identical), ARF3 (30% identical), ARL4A (30% identical), ARL1 (29% identical), ARL3 (29% identical), and 18 more.
Diseases named in the same sentence as SAR1A in open-access papers:
SAR1A is named in the same sentence as 25 diseases in open-access papers, as found by Europe PMC text mining. Sharing a sentence is not in itself a finding about the gene and the disease. The quoted sentences say what the papers report.
Alzheimer disease (2 papers, 2017 to 2025). A progressive, neurodegenerative disease characterized by loss of function and death of nerve cells in several areas of the brain leading to loss of cognitive function such as memory and language. "Furthermore, SAR1a was identified as a potential biomarker in Alzheimer's disease, with differential expression in human brains with Alzheimer's disease." (PMID 41488750, 2025). "Gene-based tests conducted in the CCS and Alzheimer’s Disease Neuroimaging Initiative (ADNI) samples using SKAT-O resulted in a significant association for RAB10 (p value = 0.002), but not SAR1A (p value = 1.00)." (PMID 29183403, 2017).
Anderson's disease (2 papers, 2011 to 2023). "In contrast, the level of expression of SAR1A was significantly (p < 0.01) increased (between 1.4 and 2.7 fold) in the biopsies of the Anderson's disease patient as compared to biopsies of the same healthy individuals, except for individual NA1." (PMID 21235735, 2011). "Finally, for the first time, we describe the differential expression of the SAR1A and SAR1B genes and the localization of the Sar1 proteins in the enterocytes of intestinal biopsies from Anderson's disease patients as compared to healthy individuals." (PMID 21235735, 2011).
fatty liver (2 papers, 2011 to 2014). "Because clinical studies have indicated that SAR1B mutations affect chylomicron secretion and, despite intestinal fat malabsorption, some children with CMRD develop fatty liver (2, 16, –, 18), we examined relative SAR1A and SAR1B mRNA levels in human intestinal biopsies and liver samples." (PMID 24338480, 2014).
glioblastoma (2 papers, 2019 to 2024). The most malignant astrocytic tumor (WHO grade IV). "In addition to steroid hormone synthesis, CYP17A1 associates with SAR1a/b to regulate protein processing and maintain ER health in glioblastomas." (PMID 31527549, 2019). "Herein, we identified a novel function of CYP17A1 that is independent of steroidogenesis, and showed that CYP17A1 maintains the survival of glioblastomas by regulating SAR1a/b-mediated protein processing in the ER." (PMID 31527549, 2019). "In contrast, SAR1A functions as a tumor suppressor in lung cancer, liver cancer, and glioblastoma." (PMID 39595043, 2024). "Additionally, SAR1A interacts with Cytochrome P450 (CYP) 17A1 to regulate protein processing in the ER, contributing to the survival of glioblastoma cells." (PMID 39595043, 2024).
hepatocellular carcinoma (2 papers, 2022 to 2024). A malignant tumor that arises from hepatocytes. "In this study, we investigated the effects of Sar1a and Sar1b on numbers, size, and components of LDs in the human hepatoma cell line HuH7 cells." (PMID 35742827, 2022). "In hepatocellular carcinoma (HCC) cells, SAR1A interacts with TMEM176A to inhibit ERK signaling, thereby suppressing HCC cell growth." (PMID 39595043, 2024). "In malignant tumors, SAR1A exhibits complex roles, such as promoting osteosarcoma metastasis through the RhoA/YAP pathway and inhibiting ERK signaling, thereby suppressing the growth of hepatocellular carcinoma (HCC) cells." (PMID 39595043, 2024).
legionellosis (2 papers, 2017 to 2020). Any disease caused by Legionella bacteria. "In addition, HSPA8 and SAR1A connected the protection processing in endoplasmic reticulum with legionellosis pathway." (PMID 32632500, 2020). "The legionellosis pathway may have reached significance because of the presence of the genes Sar1a and Vcp that are also present in the protein processing in endoplasmic reticulum pathway." (PMID 28125669, 2017).
osteosarcoma (2 papers, 2023 to 2024). A usually aggressive malignant bone-forming mesenchymal neoplasm, predominantly affecting adolescents and young adults. "SAR1A is upregulated in colon cancer and osteosarcoma, where it promotes osteosarcoma cell metastasis through the RhoA/YAP pathway, ER stress, and autophagy." (PMID 39595043, 2024). "Further correlation analysis found BNIP3 to have a significantly positive correlation with MYC, NELL1, SAR1A, PLOD2, and other genes proven to promote osteosarcoma metastasis." (PMID 37190333, 2023).
Anxiety (1 paper, 2021). Intense feelings of nervousness, tension, or panic often arise in response to interpersonal stresses. "Interestingly, among the anxiety- and depression-related DEGs, we found the upregulation of Bcl3, C3, Gpat3, and Tnf in the AMY as well as the increased expression of Crhr2, Nant, Sar1a, and Tgif1 and the decreased expression of Ier2, Il12a, Nrep, and Tnfrsf25 in the ACC." (PMID 33898422, 2021).
centronuclear myopathy (1 paper, 2023). Centronuclear myopathy (CNM) is an inherited neuromuscular disorder characterized by clinical features of a congenital myopathy and centrally placed nuclei on muscle biopsy. "This increased expression of SAR1A is specific to KLHL40-deficient skeletal muscle as analysis of skeletal muscle from centronuclear myopathy patients (RYR1 or MTM1 disease-causing mutations) showed no changes in the SAR1A protein levels compared to the control." (PMID 37432316, 2023).
neuroblastoma (1 paper, 2017). Neuroblastoma (NB) is the most common solid, extracranial childhood tumor. "To examine previous reports of biochemical interactions between RAB10 and APP and between SAR1A and APP, we examined the effects of overexpressing and silencing RAB10 and SAR1A on APP processing in mouse neuroblastoma cells." (PMID 29183403, 2017).
psoriasis (1 paper, 2024). An autoimmune condition characterized by red, well-delineated plaques with silvery scales that are usually on the extensor surfaces and scalp. "Then, the expression of top 5 potential candidate genes (PBX1, CYB5R4, SAR1A, CXCR5, MFSD6) of miR-3074-5p was detected in normal and psoriasis tissues by qPCR; our result revealed that PBX1 was the most upregulated genes in psoriasis tissues compare to normal ones." (PMID 38240925, 2024).
tumor (4 papers, 2019 to 2024). "SAR1A exhibits high expression levels in various tumor types, yet its specific role in HNSCC remains to be clarified." (PMID 39595043, 2024). "The outcome module in the TIMER2.0 software evaluated the clinical relevance of tumor immune subsets and SAR1A expression levels in HNSCC." (PMID 39595043, 2024). "We generated and confirmed at genomic and mRNA levels the BTRC-MGMT and SAR1A-MGMT fusion events in the MGMT-negative patient-derived h543 GBM tumor spheres." (PMID 32753598, 2020). "Subsequently, we found that overexpression of SAR1 significantly prevented abiraterone-induced cell death, suggesting that the tumor-suppressive effect of CYP17A1 inhibition is mediated by the downregulation of SAR1a/b." (PMID 31527549, 2019). "Therefore, circ-SAR1A suppression, causes an overexpression of miR-382, which blocks YBX1 expression, thus preventing tumor expansion." (PMID 35813211, 2022). "In addition, functional experiments performed in vitro demonstrated that circ-SAR1A suppression caused a decrease in cell growth and invasion, by circ-SAR1A sponging miR-382, which targets YBX1 and reduces its expression, promoting RCC tumor growth and invasion." (PMID 35813211, 2022).
cancer (2 papers, 2024). A tumor composed of atypical neoplastic, often pleomorphic cells that invade other tissues. "While previous studies have explored the role of SAR1A in various cancers, its specific implications in HNSCC have remained unclear." (PMID 39595043, 2024).
infection (2 papers, 2013 to 2021). The state of being infected such as from the introduction of a foreign agent such as serum, vaccine, antigenic substance or organism. "In contrast, a dominant-active mutant of Sar1a, which allowed COPII vesicle formation but inhibited the secretory pathway by stabilizing COPII coats, caused major disruption to the ER–Golgi intermediate compartment (ERGIC) but did not inhibit infection." (PMID 23963534, 2013).
metabolic disease (1 paper, 2024). A congenital disorder (due to inherited enzyme abnormality) or acquired (due to failure of a metabolically important organ) disorder resulting from an abnormal metabolic process. "In metabolic diseases, SAR1A mutations impair insulin processing, leading to ER stress." (PMID 39595043, 2024). "SAR1A is involved in various physiological and pathological processes, including neurological disorders, metabolic diseases, circulatory function, muscle development, hematological disorders, and multiple cancers." (PMID 39595043, 2024).
neurological diseases (1 paper, 2024). "For example, in neurological diseases, SAR1A levels are significantly reduced in Alzheimer’s disease (AD)." (PMID 39595043, 2024).
SAR1A also shares sentences with these, for which no sentence is quoted: sickle cell disease (2 papers); colon cancer (1); colorectal cancer (1); depression (1); head and neck squamous cell carcinoma (1); Hurler syndrome (1); liver cancer (1); lung carcinoma (1); pulmonary hypertension (1).